EYA4 (EYA transcriptional coactivator and phosphatase 4)
Description:
Tyrosine phosphatase that specifically dephosphorylates 'Tyr-142' of histone H2AX (H2AXY142ph). 'Tyr-142' phosphorylation of histone H2AX plays a central role in DNA repair and acts as a mark that distinguishes between apoptotic and repair responses to genotoxic stress. Promotes efficient DNA repair by dephosphorylating H2AX, promoting the recruitment of DNA repair complexes containing MDC1. Its function as histone phosphatase probably explains its role in transcription regulation during organogenesis. May be involved in development of the eye (By similarity).
Synonyms: CMD1J; DFNA10
Tractability: PROTAC: UniProt records ubiquitination sites on it; ubiquitination databases record sites on it.
Gene: Protein-coding gene on chromosome 6 (133,240,514 to 133,532,128, forward strand). Ensembl gene ENSG00000112319.
Subcellular location: Cytoplasm; Nucleus
Subcellular location (Human Protein Atlas): Nucleoplasm
Pathways (Reactome):
DNA Repair: Recruitment and ATM-mediated phosphorylation of repair and signaling proteins at DNA double strand breaks
Gene Ontology:
Molecular function: protein binding; protein tyrosine phosphatase activity
Biological process: anatomical structure morphogenesis; cell differentiation; negative regulation of extrinsic apoptotic signaling pathway in absence of ligand; positive regulation of DNA repair; visual perception; inner ear development
Cellular component: cytoplasm; nucleus
Genetic constraint (gnomAD): Loss-of-function variants: 20 observed, 54.25 expected, observed/expected ratio (o/e) 0.37, 90% interval 0.26 to 0.54. The upper end of that interval is the gene's LOEUF score, 0.54, which puts it in group 2 of 6, group 1 being the genes least tolerant of losing a copy. Missense variants: 462 observed, 544.27 expected, observed/expected ratio (o/e) 0.85, 90% interval 0.79 to 0.92. Synonymous variants: 187 observed, 197.77 expected, observed/expected ratio (o/e) 0.95, 90% interval 0.84 to 1.07.
Gene-disease validity (ClinGen):
ClinGen rates the evidence that EYA4 causes each of these diseases.
nonsyndromic genetic hearing loss (autosomal dominant): Definitive.
dilated cardiomyopathy 1J (autosomal dominant): Limited. An extremely rare autosomal dominant syndrome described in two families to date and characterized by moderate to severe sensorineural hearing loss manifesting during childhood, and associated with late-onset dilated cardiomyopathy that generally progresses to heart failure.
Homologues: Orthologues: chimpanzee EYA4 (99% identical), pig EYA4 (98% identical), dog EYA4 (97% identical), rabbit EYA4 (97% identical), guinea pig EYA4 (97% identical), rat Eya4 (97% identical), mouse Eya4 (97% identical), macaque EYA4 (95% identical), tropical clawed frog eya4 (88% identical), zebrafish eya4 (76% identical), Drosophila melanogaster eya (43% identical), Caenorhabditis elegans eya-1 (21% identical). Paralogues in human: EYA1 (68% identical), EYA2 (50% identical), EYA3 (48% identical).
Diseases named in the same sentence as EYA4 in open-access papers:
EYA4 is named in the same sentence as 58 diseases in open-access papers, as found by Europe PMC text mining. Sharing a sentence is not in itself a finding about the gene and the disease. The quoted sentences say what the papers report.
hearing loss (25 papers, 2012 to 2025). "We analyzed the novel gene pair EYA4 and MUS81, where EYA4, involved in transcription, eye development, and DNA repair, is linked to hearing loss and cardiomyopathy, while MUS81 is essential for DNA repair." (PMID 39372928, 2024). "Further, EYA4 mutations have been associated with increased vulnerability to noise-induced hearing loss in occupational settings." (PMID 37885485, 2023). "The 15 associations included a missense lead variant in TMPRSS3, a known cause of Mendelian hearing loss, adding to the tally of Mendelian deafness genes (EYA4, CDH23, TRIOBP) showing common coding-variant associations with hearing loss in adult humans." (PMID 35661827, 2022). "Our results expanded the variant spectrum and genotype‒phenotype correlation of the EYA4 gene and autosomal dominant nonsyndromic hereditary hearing loss in Chinese Han individuals." (PMID 35578334, 2022). "The prevalence of EYA4-associated hearing loss in ADNSHL was 0.90% (12/1,334 cases) in the Japanese population." (PMID 32107406, 2020). "We also analyzed the rate of hearing deterioration in EYA4-associated hearing loss patients identified in this study and previously reported cases." (PMID 32107406, 2020). "Based on this, we estimated the incidence of EYA4-associated hearing loss was 0.90% in Japanese families with autosomal dominant hearing loss." (PMID 32107406, 2020). "To better understand the clinical characteristics and prevalence of DFNA10, we performed genetic screening for EYA4 mutations in a large cohort of Japanese hearing loss patients." (PMID 32107406, 2020). "In this study, we sought to elucidate the variant spectrum of the EYA4 gene and prevalence of EYA4-associated hearing loss in the Japanese population, and to obtain a more precise description of the clinical features of EYA4-associated hearing loss." (PMID 32107406, 2020). "In this report, we analyzed 1,334 ADNSHL patients and identified 12 candidate variants for EYA4-associated hearing loss." (PMID 32107406, 2020). "In this study, WES was used to find the disease-causing gene of a large Chinese family with hearing loss, and we identified the EYA4 exon 8 missense mutation in all cases." (PMID 25961296, 2015). "The locus is relatively close to EYA4 (DFNA10), however a meiotic cross-over in three affected individuals excluded DFNA10 as the cause of the hearing loss in this family, consistent with the initial sequencing where no variations were found in EYA4." (PMID 26197441, 2015). "Interestingly, mutations in the human EYA4 were found to cause late-onset hearing impairment at the DFNA10 locus." (PMID 39857604, 2024). "In rats, Eya4 expression persists in the organ of Corti and spiral prominence into the postnatal period, and people with certain EYA4 mutations exhibit late-onset hearing loss." (PMID 37885485, 2023). "The contribution of EYA4 variants to hearing loss has been well established." (PMID 35580588, 2022). "This is the largest population studied for EYA4-associated hearing loss to date." (PMID 32107406, 2020). "The sole phenotype resulting from mutations in the EYA4 gene is hearing loss." (PMID 25781927, 2015). "Several mutations in the EYA4 had been found to be associated with progressive and hearing loss." (PMID 26400775, 2015). "Eleven novel EYA4 variants (three frameshift variants, three missense variants, two nonsense variants, one splicing variant, and two single-copy number losses) and two previously reported variants were found in 12 probands (0.90%) among the 1,336 autosomal dominant hearing loss families." (PMID 32107406, 2020). "Defective apoptotic activity caused by EYA4 mutations may also lead to human DFNA10 hearing loss." (PMID 25961296, 2015). "Recent genetic analyses in older populations have revealed a significant enrichment of rare EYA4 variants among individuals with ARHL, suggesting its possible involvement in the genetic architecture of common, late-onset hearing impairment." (PMID 41255877, 2025).
hearing loss (continued). "Mutations in hereditary deafness genes, such as TRIOBP, ILDR1, and EYA4, also exhibited significant correlations with age-related hearing impairment." (PMID 37062025, 2023). "Of the 16 hair cell-specific risk genes identified in our analysis, loss-of-function mutations in two are known to cause Mendelian hearing loss: TRIOBP and EYA4." (PMID 32986727, 2020). "Thus, we speculated that the mechanism of EYA4-associated hearing loss was haploinsufficiency." (PMID 32107406, 2020). "The EYA4 gene (OMIM* 603550), located on chromosome 6q22.3-q23.2, for DFNA10 (OMIM# 601316) was first identified in American and Belgian hearing loss patients in 20014." (PMID 32107406, 2020). "The purpose of this study was to examine the associations between genetic variations in the EYA4, GRHL2 and DFNA5 genes and the risk to noise-induced hearing loss (NIHL) in a Chinese population." (PMID 26400775, 2015). "Our results provide additional molecular and clinical information in order to gain improved understanding of the pathogenesis of EYA4 mutations and the genotype-phenotype correlations of DFNA10 hearing loss." (PMID 25242383, 2014). "Second, our findings point to multiple genes that have been reported to cause Mendelian forms of hearing loss previously, including EYA4, CDH23, TRIOBP, and GJB2, the latter being the most commonly reported gene in autosomal-recessive non-syndromic hearing loss." (PMID 35580588, 2022). "Further mutations in EYA4, a transcriptional coactivator, could cause syndromic DCM with sensorineural hearing loss." (PMID 35527250, 2022). "Autosomal dominant non-syndromic hearing loss is highly heterogeneous, and eyes absent 4 (EYA4) is a disease-causing gene." (PMID 25961296, 2015). "Aside from mutation c.T1301A in EYA4 gene, none of the other 19 candidate variants was detected to be co-segregated with the hearing loss phenotype of family JSNY-023." (PMID 25242383, 2014).
deafness (16 papers, 2007 to 2023). An inherited or acquired condition characterized by the complete loss of the ability to hear from one or both ears. "One of the genes associated with deafness is the eyes absent homolog 4 (EYA4) gene, a transcription factor related to the development and function of the inner ear." (PMID 37251241, 2023). "The phenotype of EYA4-causing syndromic or non-syndromic deafness is correlated with the position of the mutation." (PMID 25961296, 2015). "However, in some cases, EYA4 variants result in cardiac phenotypes, including dilated cardiomyopathy and a Mobitz type II AV block with deafness." (PMID 36140227, 2022). "Genes already associated with hearing or deafness (mouse and/or zebrafish) were selected as controls/references for comparison and validation of the candidate genes’ results: Eya4 (DFNA10), Gsdmea (DFNA5), Gsdmeb (DFNA5), Pou4f1, Elavl4, Sclla3a, Gab1 (DFNB26), and Mettl1 (DFNM)." (PMID 36553541, 2022). "By further study, the group identified EYA4 gene mutations in two unrelated families from Belgium and the USA segregating for deafness at this locus; they found different mutations in EYA4, c.1468insAA (p.342 fs) and c.2200C > T (p.R587X), both of which create premature stop codons." (PMID 25963406, 2015). "Though most of the reported EYA4 mutations are truncating mutations leading to haploinsufficiency, at least four EYA4 missense mutations have been reported to lead to non-syndromic deafness DFNA10." (PMID 34956325, 2021). "Most EYA4 mutations founded in the Eya-homologous region, however, no deafness causative missense mutation in variable region of EYA4 have previously been found." (PMID 25961296, 2015). "A detailed genotype and phenotype analysis of EYA4 in deafness is provided." (PMID 25963406, 2015). "Our study also expands the genotypic spectrum of EYA4 in DFNA10, by adding four novel variants (c.697C>T:p.Gln233Ter, c.208+1del, c.578dup:p.Tyr193Ter, and c.1468G>T:p.Glu490Ter), all of which were associated with moderate to severe non-syndromic deafness characterized by gradual hearing loss." (PMID 36140227, 2022).
colorectal cancer (10 papers, 2016 to 2024). A primary or metastatic malignant neoplasm that affects the colon or rectum. "Specifically, in colorectal cancer, EYA4 and ADHFE1 have already been validated as hypermethylated and down-regulated genes." (PMID 37628872, 2023). "Using genome-wide expression array, they screened out abnormal expression of genes involved in the Wnt, mitogen-activated protein kinase (MAPK), and local adhesion signal pathways in EYA4-overexpressing colorectal cancer cells." (PMID 27469137, 2016). "In addition, the EYA4 gene has also been identified as a promising tumor suppressor gene for colorectal cancer since it controls DKK1 upregulation and blocks the Wnt signaling pathway." (PMID 37156847, 2023). "Recent studies have shown that abnormal methylation of the EYA4 gene may be a biomarker for colorectal cancer, urothelial bladder cancer, and breast cancer." (PMID 37156847, 2023). "In malignant peripheral nerve sheath tumors (MPNST) EYA4 is over-expressed, whilst it is down-regulated in esophageal adenocarcinoma, hepatocellular carcinoma, lung cancer and colorectal cancer, where the EYA4 gene promoter has been found to be hypermethylated." (PMID 37292941, 2023). "They found that EYA4 overexpression could inhibit the growth of colorectal cancer cells both in vitro and in vivo." (PMID 27469137, 2016). "Previous studies have demonstrated that EYA4 acts as a tumor suppressor gene in non-small cell lung cancer, colorectal cancer, hepatocellular carcinoma, esophageal squamous cell carcinoma and pancreatic ductal adenocarcinoma, but the biological role of EYA4 in BC remains unknown." (PMID 31101108, 2019). "Fusobacterium nucleatum, a gram-negative anaerobic bacillus, is mainly associated with colorectal cancer patients positive for the CpG island methylator phenotype, although hypermethylation in genes such as MLH1, CDKN2A, MTSS1, RBM38, PKD1, PTPRT, and EYA4 has also been described." (PMID 37614819, 2023).
hepatocellular carcinoma (8 papers, 2016 to 2024). A malignant tumor that arises from hepatocytes. "Our previous studies demonstrated that eyes absent homolog 4 (EYA4), a member of the eye development-related EYA family in Drosophila, is frequently methylated and silenced in hepatocellular carcinoma (HCC) specimens and associated with shorter survival." (PMID 29764501, 2018). "For instance, overexpression of EYA4 suppresses the c-JUN-mediated angiogenesis and metastasis of hepatocellular carcinoma (HCC) in nude mice." (PMID 36741265, 2023). "Using DNA methylation microarray, our previous study showed that the EYA4 gene was markedly hypermethylated in hepatocellular carcinoma (HCC) tissues compared with adjacent non-tumorous tissues." (PMID 27469137, 2016). "Eye absent homolog 4 (EYA4) has been demonstrated to be down‐regulated in hepatocellular carcinoma (HCC), but its biological function and the mechanism in HCC angiogenesis and metastasis remain largely unknown." (PMID 30957411, 2019).
bladder cancer (7 papers, 2019 to 2023). "For example, circACVR2A inhibits tumor progression by interacting with miR‐626 and promotes target EYA4 expression in bladder cancer." (PMID 36530171, 2023). "circACVR2A functions as a tumor suppressor to inhibit bladder cancer cell proliferation and metastasis through miR-626/EYA4 axis, suggesting that circACVR2A is a potential prognostic biomarker and therapeutic target for bladder cancer." (PMID 31101108, 2019). "It was reported that circACVR2A inhibited bladder cancer development via the miR-626/EYA4 axis." (PMID 34811346, 2021). "In bladder cancer, circ-ACVR2A could directly interact with miR-626 and acts as a miRNA sponge to regulate EYA4 expression, thus inhibiting bladder cancer cell proliferation and metastasis." (PMID 33613544, 2020). "Previously, researches demonstrated circRNA ACVR2A suppresses bladder cancer progression through regulating miR-626/EYA4 axis; CircRNA INTS4 promotes tumorigenesis in bladder cancer via miR-146b/CARMA3 axis." (PMID 33656636, 2022).
dilated cardiomyopathy (7 papers, 2008 to 2023). Cardiomyopathy which is characterized by dilation and contractile dysfunction of the left and right ventricles. "Mutations of the EYA4 gene resulting in truncated EYA4 proteins cause dilated cardiomyopathy and conductive hearing loss in humans and Eya4 mutations in mice are responsible for an abnormal morphology of the middle ear." (PMID 19102749, 2008). "In addition, the EYA4 variant reportedly causes dilated cardiomyopathy accompanying NSHL in a single large family." (PMID 35578334, 2022). "In addition, EYA4 mutation was also reported to cause dilated cardiomyopathy accompanying SNHL in a single large family." (PMID 25242383, 2014). "Three of our five EYA4 variants were predicted to encode truncated proteins affecting the eya-VR domain, but cardiac evaluations in these patients showed no signs of dilated cardiomyopathy." (PMID 36140227, 2022). "The EYA4 gene is known to be responsible for both nonsyndromic deafness DFNA10 and syndromic deafness with dilated cardiomyopathy." (PMID 30123251, 2018). "Including our work, many studies indicated that the genotype–phenotype correlation of large deletions in EYA4 and dilated cardiomyopathy was not very obvious." (PMID 35578334, 2022). "In addition, a family with dilated cardiomyopathy and SNHL was found to have a large deletion in EYA4 that also led to a frameshift." (PMID 25961296, 2015).
lung carcinoma (7 papers, 2011 to 2024). "The frequency of epimutation is highly contrasting as 59% of CRC patients carry hypermethylated EYA4 promoters compared with only 13% of lung cancer patients." (PMID 38475971, 2024). "In most mouse strains, knockout of EYA4 is lethal shortly after birth and is toxic in several lung cancer cell lines and other cell lines that we tested." (PMID 37292941, 2023). "EYA1 is overexpressed in Wilms’ tumors, EYA2 is overexpressed in epithelial ovarian cancers and lung carcinoma, and EYA4 overexpression has been detected in MPNST (malignant peripheral nerve sheath tumor)." (PMID 29340020, 2017). "Recently, the EYA4 gene was found to be hypermethylated in some malignancies, including esophageal, colorectal, and lung carcinoma." (PMID 27469137, 2016).
autosomal dominant non-syndromic hearing loss (6 papers, 2015 to 2022). "EYA4 maps to the autosomal dominant non-syndromic hearing loss (NSHL) locus DFNA10 on chromosome 6q23." (PMID 25781927, 2015). "EYA4 mutations generally cause autosomal dominant non-syndromic deafness (DFNA10)." (PMID 36140227, 2022). "In this study, we have performed the mutational screening of EYA4 gene by DHLPC and NGS in a large cohort of 531 unrelated Spanish probands and one Australian family with autosomal dominant non-syndromic hearing loss (ADNSHL)." (PMID 32277154, 2020). "In this study, we performed a genetic analysis of EYA4 and GRHL2 in 87 unrelated Korean patients with autosomal dominant non-syndromic hearing loss (NSHL)." (PMID 25781927, 2015).
cardiomyopathy (5 papers, 2013 to 2024). A disease of the heart muscle or myocardium proper. "EYA4-deficient mice exhibit severe hearing deficits and develop otitis media with effusion, which may resemble the effects of the EYA4 mutations, which cause sensorineural hearing loss accompanied by cardiomyopathy in humans." (PMID 23443160, 2013). "This shows that interruption of the EYA4 interaction with SIX1 and SIX2 impairs cardiac function, resulting in cardiomyopathy." (PMID 25781927, 2015). "However, the shorter E193 (causing the deletion of a 4846-bp region that includes the last nucleotide of exon 9, intron 9, exon 10, and part of intron 10) caused NSHL and cardiomyopathy because these mutated proteins did not bind SIX proteins and could not dimerize with full-length EYA4." (PMID 25781927, 2015).
esophageal adenocarcinoma (5 papers, 2009 to 2023). A malignant tumor with glandular differentiation arising predominantly from Barrett mucosa in the lower third of the esophagus. "Recently, the value of methylated EYA4 as a marker for Barrette's esophagus and esophageal adenocarcinoma has been suggested." (PMID 19939248, 2009).
adenoma (4 papers, 2014 to 2025). A neoplasm arising from the epithelium. "Luo and colleagues compared methylomes of the normal colon mucosa, tubular adenomas, as well as CRC and reported hypermethylation of EYA4 cg01328892 in CRC and adenoma compared to normal." (PMID 32380793, 2020). "Detection of faecal methylated DNA has also been examined for CRC detection such as the eyes absent homolog 4 (EYA4) that was found to have a sensitivity of 100% (13/13) for CRC detection and 76.9% (27/35) for advanced adenoma, with a specificity of 94.7% (18/19)." (PMID 30944663, 2019).